RN7SL70P (RNA, 7SL, cytoplasmic 70, pseudogene)
Gene: Miscellaneous RNA gene on chromosome 19 (18,957,957 to 18,958,258, reverse strand). Ensembl gene ENSG00000241172.
Homologues: Orthologues: chimpanzee Metazoa_SRP (98% identical), macaque Metazoa_SRP (93% identical). Paralogues in human: RN7SL1 (83% identical), RN7SL2 (83% identical), RN7SL3 (82% identical), RN7SL147P (80% identical), RN7SL357P (79% identical), RN7SL122P (79% identical), RN7SL15P (79% identical), RN7SL18P (79% identical), RN7SL769P (79% identical), RN7SL126P (78% identical), RN7SL230P (78% identical), RN7SL296P (78% identical), and 703 more.